VIM (vimentin)
Diseases named in the same sentence as VIM in open-access papers (continued):
Sharing a sentence is not in itself a finding about the gene and the disease.
cancer (continued). "As EMT phenotype of chemoresistant cancer cells has been documented, it is not surprising that the mRNA and protein expression levels of Snail, Slug, ZEB1, Vimentin, and Fibronectin were higher in GR cells compared with parental cells." (PMID 31783584, 2019). "Although we evaluated EMT in vitro based on downregulation of E-cadherin and upregulation of vimentin, we have not evaluated EMT of cancer cells in vivo." (PMID 31040369, 2019). "Although we did not observe obvious morphological changes in cancer cells after miR-182 overexpression, the EMT marker proteins, namely CDH1, CDH2 and Vimentin, were modestly regulated by miR-182." (PMID 27996004, 2016). "Without vimentin to coordinate the cytoskeleton webs into the appropriate types of architecture and stabilize focal adhesions, EMT-cancer cells were unable to generate appropriate cellular force and form cell polarity for further tumorigenesis." (PMID 25965826, 2015). "While vimentin is not a direct target of miR-155, C/EBPβ, a well-established miR-155 target plays a role in EMT in various cancers." (PMID 26042593, 2015). "Western blot analysis confirmed that CLA carcinomas were Vimentin (VIM) positive, KRT19/CDH1 negative, while CLB carcinomas were VIM negative, KRT19/CDH1 positive." (PMID 26158412, 2015). "The results showed that the cancer cells in the lymphatic vessels expressed vimentin more extensively than those in the adenocarcinoma components without an MPP, suggesting that cancer cells derived from an MPP component are present in the lymphatic vessels." (PMID 25120667, 2014). "The grade of vimentin expression in each lymphatic vessel was higher than that in the non-MPP component, indicating that the cancer cells detected in the MPP component are also present in the lymphatic vessels." (PMID 25120667, 2014). "Most slides from cancer-free tissue lacked expression of CCND1, CD44, CDH1, EGFR, ERBB2, KIT, keratins, NOTCH1, PAK1, PTGS2, SNAI1, and VIM but showed staining of MUC1, HIF1A, NKX2-1, SFTPC, and STAT3, which were also found in AdCa." (PMID 23028920, 2012). "One of these patients had 4 foci, 2 of which were BLBCs while the other two were TN carcinomas without expression of basal keratins, EGFR or vimentin." (PMID 23082819, 2012). "All nine patients whose cancers lacked immunohistochemical reactivity for both myosin IIA and vimentin showed relapse-free survival at 5 years." (PMID 18212748, 2008). "Immunohistochemical evaluation of sample set A: all patients with cancers lacking expression of both myosin IIA and vimentin showed relapse-free survival at 5 years." (PMID 18212748, 2008). "Our study revealed increased expression of c-Myc together with high expression of the mesenchymal markers VIM (Vimentin), FN1 (Fibronectin), ZEB2 (SIP-1), FOXC2, SNAIL1 (Snail), SNAIL2 (Slug), and TWIST and the cancer stem-like cell marker CD44 in cells and tumors lacking MCPIP1 RNase activity." (PMID 39815326, 2025). "However, metastatic lymph nodes contained viable undifferentiated carcinoma cells that were negative for hepatocellular markers (HepPar-1 and arginase-1) but positive for CAM5.2 and vimentin, indicating a treatment-resistant component." (PMID 41415330, 2025). "However, the expression of E-cadherin in the recurrent tissue was positive and that of vimentin was negative, suggesting that EMT was not present in the recurrent cancer tissue." (PMID 36867254, 2023). "Unlike conventionally sized diploid cancer cells, PGCC daughter cells exhibit mesenchymal properties with a high expression of mesenchymal cell markers, including N-cadherin, twist, slug, snail, and vimentin." (PMID 37833712, 2023). "Vimentin expression is not directly involved in the treatment of this neoplasm, but it has a key role in the EMT process, which seems to be involved in resistance to various cancer treatments." (PMID 34917615, 2021).
cancer (continued). "Therefore, in the present study, we also investigated the role of extracellular vimentin in SARS-CoV-2 infection, particularly as viral shedding of coronavirus is greater in patients with cancers compared to those without." (PMID 34299089, 2021). "Interestingly, with the SARS-CoV-2 RBD and 10 nM of vimentin preincubation, the monolayer permeability alteration was not affected for the MCF-10a control cells, but it was inhibited for the MCF-7 cancer cells." (PMID 34299089, 2021). "Moreover, MAs upregulated α5β1 integrin expression on PFBs but not on PMCs or cancer cells, vimentin expression in all cells tested, and ICAM-1 only in cancer cells." (PMID 33921783, 2021). "Moreover, compared to the non-treated cells, the expression of cancer markers including CK8, CA-125, and vimentin, was lower in the A. helianthus extract-treated cells." (PMID 32513981, 2020). "Our results show that no changes were found in E-cadherin and Vimentin between ADH and CSCs, which may be due to the fact that cancer cells are able to switch between different phenotypic states." (PMID 32863948, 2020). "Moreover, Vimentin showed no significant change in both MLN4924 treated and si-N8 transfected cancer cell lines." (PMID 33097763, 2020). "Interestingly, we also observed a small number of CD90+ cells that were negative for αSMA and VIM, suggesting that there was a different population of CD90+ cells in the cancer." (PMID 24116172, 2013). "On IHC, diffuse positivity with vimentin and lack of CK, EMA, CK7 ruled out a carcinoma." (PMID 20233457, 2010). "However, Vimentin expression in DU145 cells, was not significantly affected by either TGF-β1 or co-treatment of TGF-β1 with CQ, indicating that each cancer cell might differently respond to TGF-β1." (PMID 36230768, 2022).
infection (194 papers, 2007 to 2026). The state of being infected such as from the introduction of a foreign agent such as serum, vaccine, antigenic substance or organism. "In contrast, Escherichia coli and Shigella flexneri, which are classified as pathogens, induced less vimentin expression in HaCaT cells compared to S. aureus and caused approximately 40 to 80 times less intracellular infection." (PMID 40061451, 2025). "Given the critical role of vimentin in the life cycle of S. aureus, there is potential for the development of therapeutics that target vimentin to manage intracellular infections caused by this pathogen." (PMID 40061451, 2025). "Lastly, we discuss the therapeutic approaches associated with vimentin targeting, leading to several beneficial effects such as preventing infection, limiting inflammatory responses, or the progression of cancerous events." (PMID 37475865, 2023). "Therapeutic targeting of vimentin is promising in cases of vimentin hijacking by pathogenic mechanisms, including infection and tumorigenesis." (PMID 37475865, 2023). "Influenza A virus, the causative agent of seasonal flu epidemics, reorganizes the vimentin network after infection of the host cell." (PMID 37475865, 2023). "We report that several viruses from the human enterovirus group B cause massive vimentin rearrangements during lytic infection." (PMID 31619557, 2020). "Several research groups have reported the spatial association of vimentin with viruses during infection, particularly near the replication area and progeny virus production (12, –, 34)." (PMID 31619557, 2020). "It associated more strongly with the vimentin cage during infection but spread out to all cytoplasm, showing lower signal during IDPN treatment." (PMID 31619557, 2020). "Infection of primary rat epithelial cell cultures with periodontal pathogens for 8 days caused an enhanced percentage of vimentin-positive cells, 20% after stimulation with P. gingivalis and 30% after infection with F. nucleatum." (PMID 30837987, 2019). "Here, we report that the intermediate filaments, keratin and vimentin, assemble on the ApV early and remain associated with the ApV throughout infection." (PMID 29056733, 2016). "Given that vimentin plays a crucial role in intracellular infections caused by viruses and bacteria, we chose to further investigate vimentin, which was shown to be statistically and dose-dependently elevated by S. aureus, to evaluate its impact on S. aureus infection in HaCaT cells." (PMID 40061451, 2025). "In addition, it has been reported that desmin and vimentin are associated with the infection of TMEV, a neurotropic murine picornavirus." (PMID 36851648, 2023). "In addition, vimentin exerted more significant effects on multiple infection processes of the velogenic variant NDV strain." (PMID 37848995, 2023). "Moreover, vimentin was required for multiple infection processes of the variant NDV strain in HD11 cells, including viral internalization, fusion, and release, while it was not necessary for those of the prototypic NDV strain." (PMID 37848995, 2023). "The distribution of vimentin is involved in the infection of various pathogenic bacteria." (PMID 36717839, 2023). "However, anti-vimentin antibodies will certainly be an effective therapeutic strategy for SARS-CoV-2 by blocking the infection of variants or reducing clinical symptoms." (PMID 35646741, 2022). "Extensive research in vimentin-deficient animal models has unveiled its involvement in response to injury or stress, with implications in wound healing, inflammation and immune response, atherosclerosis, fibrosis or infection." (PMID 32630064, 2020). "Regarding its implications in infection, as it will be detailed below, pathogens and/or the associated damage can induce vimentin expression and/or surface exposure, which, in turn could hypothetically contribute to infection." (PMID 32630064, 2020).
infection (continued). "Several viruses have been shown to cause changes in the cellular vimentin network during infection." (PMID 31619557, 2020). "Furthermore, during in vivo infection, L. monocytogenes is deficient in colonization of the brains of vimentin knockout mice." (PMID 29487235, 2018). "In addition, loss of vimentin has been reported to reduce inflammation and infection (for references)." (PMID 30248895, 2018). "Based on this study, we could hypothesize that some EV71 associated syndromes may be attributed to the vimentin rearrangement and mis-regulation of CaMK-II during infection." (PMID 24073199, 2013). "Immunofluorescence (IF) images demonstrated that vimentin was associated with S. aureus in the cytoplasm and on the cell surface, indicating that the binding of S. aureus to vimentin may impact the intracellular infection of S. aureus in HaCaT cells." (PMID 40061451, 2025). "Thus, we hypothesize that DTMUV infection triggers apoptosis-linked kinase activity to induce vimentin fragmentation and promote apoptosis, positioning vimentin as a molecular switch that coordinates structural defense and cell fate decisions." (PMID 41516263, 2025). "It was previously demonstrated that the infection of HEK 293T-hsACE2 cells with the SARS-CoV-2 B.1.1.7 variant with the Wuhan-Hu-1 spike protein could be blocked by 50% when the pseudovirus was first incubated with soluble vimentin." (PMID 39057066, 2024). "After infection and growth of T.cruzi amastigotes, those cellsexpress larger amounts of vimentin, with heavy staining of cytoplasm outsidethe parasitophorous vacuole and some particle shadowing patterns, suggestingthat vimentin are associated with cell cytoplasm." (PMID 29538505, 2018). "Although vimentin is thought to be involved in bacterial infection, evidence for infection mechanism through the interaction of vimentin and S. aureus in skin keratinocytes is unclear." (PMID 40061451, 2025). "During late infection, the cage-like vimentin structure that forms around the viral VRCs exhibits a context-dependent duality, functioning as either a pro-viral “shield” or an anti-viral “sabotage” strategy." (PMID 41516263, 2025). "We detected the mRNA and protein levels of vimentin in cells transfected for 48 h and in spinal cord tissue at 14 days post‐infection (dpi)." (PMID 39753767, 2025). "Following infection with the parasite in vivo, there was reduced vimentin expression in the murine vaginal tract, suggesting the parasite’s ability to impair cervical cancer progression." (PMID 39851470, 2025). "Particularly, vimentin has been demonstrated to mediate epithelial barrier opening by regulating TJs, thereby influencing infection of pathogens." (PMID 40880512, 2025). "This indicates a strong relationship between vimentin expression and the intracellular infection process of S. aureus." (PMID 40061451, 2025). "RhoA depletion markedly diminishes ROCK activity and vimentin Ser72 phosphorylation, supporting the existence of a hierarchical RhoA/ROCK-vimentin signaling axis during infection." (PMID 41516263, 2025). "Meanwhile, the mRNA in the actin was unchanged, vimentin decreased, and the infection generated a redistribution of the cytoskeleton." (PMID 40573358, 2025). "In contrast to intracellular expression, the cell surface expression of vimentin remained unchanged up to 3 h post-infection but increased by 21% after 6 h." (PMID 40061451, 2025). "In the following experiment, real-time PCR demonstrated that vimentin mRNA levels increased in a time-dependent manner, reaching approximately a nine-fold increase at 6 h post-infection, while the expression pattern of the other genes were atypical." (PMID 40061451, 2025). "Our results suggested that vimentin in control patients colonized by PJ had a similar expression pattern to that found in Plasmodium infections; that is, the infection would downregulate vimentin expression." (PMID 39997396, 2025).
infection (continued). "The phosphorylation level of Ser82 vimentin progressively increases after infection, which is correlated with viral DNA replication and late gene expression." (PMID 41516263, 2025). "Intriguingly, the efficiency of HCV cell–cell transmission exhibited a marked reduction in VIM KO cells relative to wild‐type cells when HCV nAb was applied to impede cell‐free infection." (PMID 39611409, 2025). "Depletion of vimentin resulted in a remarkable decrease in HCV infection in a simulated in vivo infection model." (PMID 39611409, 2025). "Within the CD45-ve fraction, the only mCherry+ve cells were also positive for vimentin, indicative of fibroblast infection." (PMID 41362756, 2025). "Vimentin structure serves as a critical mediator that promotes epithelial barrier dysfunction by modulating TJs, thereby playing a pivotal role in pathogen infection." (PMID 40880512, 2025). "This establishes a direct link between vimentin cage formation and a specific signaling pathway, rather than considering it a passive or secondary cellular response to infection." (PMID 41516263, 2025). "Data regarding the pathological impacts of the infection on male gonads are strong enough to encourage scientists to investigate the mechanisms by which vimentin is involved in SARS-CoV-2 pathogenesis in the testis." (PMID 39866583, 2024). "Moreover, others have shown that infection by listeria monocytogenes, foodborne bacteria that can sometimes cross the blood–brain barrier, in human microvascular endothelial cells increases with substrate stiffness and is associated with increased cell surface vimentin and increased FAK activity." (PMID 39057066, 2024). "To address the question of the mechanism of the post infection cytoskeleton remodeling, we focused on RhoA proteins and vimentin playing important regulatory and transport roles in both epithelial and endothelial cells." (PMID 39616228, 2024). "Vimentin is part of a category of genes known as immediate early genes, which are activated soon after infection and inflammation occurs." (PMID 39866583, 2024). "Vimentin proteins and other cytoskeletal filaments play significant roles in many viral replication and infection processes." (PMID 38500602, 2024). "It has also been shown that cell surface vimentin increases on infected monocytes during infection by mycobacterium tuberculosis as well as myofibroblasts and activated stellate cells during fibrosis." (PMID 39057066, 2024). "Plasma vimentin level at 70 h post-MRSA inoculation was on average twofold higher compared to pre-infection (0 h) level in the same animal." (PMID 39207603, 2024). "Our preliminary data suggest that Trametinib can disperse vimentin during the infection process, indicating a general regulatory effect of Trametinib on vimentin under both normal and pathologically stressed conditions." (PMID 38429984, 2024). "Vimentin, the most abundant intermediate filament protein, is thought to be important for regulating inflammatory responses during infection for several reasons: Vimentin is expressed in immune cells, including macrophages and neutrophils." (PMID 39139560, 2024). "It has been reported that vimentin protein is involved in the binding and infection of highly virulent strains of JEV, and monoclonal antibodies against wave proteins can inhibit JEV entry." (PMID 38500602, 2024). "Vimentin is instrumental in major histocompatibility complex (MHC)-mediated antigen presentation during pathogen infections." (PMID 38956725, 2024). "Previous studies have suggested that vimentin acts as a significant receptor or potential receptor, facilitating viral entry into the blood-brain barrier and exacerbating infection." (PMID 38500602, 2024). "For verification of the relationship between RPSA and Vimentin (VIM), the protein expression level of VIM after SS2 infection or ENO stimulation was analyzed." (PMID 38331785, 2024).